ICAM1 (intercellular adhesion molecule 1)
Diseases named in the same sentence as ICAM1 in open-access papers (continued):
Sharing a sentence is not in itself a finding about the gene and the disease.
Cerebral ischemia (continued). "Previous reports had demonstrated that blocking functional activation of ICAM-1 or in Icam1 knockout mice led to the alleviation of cerebral ischemia injury." (PMID 26175842, 2015). "The changes in the ICAM-1 protein levels in the frontal cortex after 8 min of cerebral ischemia in both the normoglycemic and diabetic hyperglycemic groups were analyzed by Western blotting." (PMID 25389378, 2014). "ICAM-1 was expressed constituently at low level in ECs, and after cerebral ischemia its expression was elevated hugely." (PMID 25315906, 2014). "The objectives of this study were to examine the mRNA and protein levels and cell type distribution of ICAM-1 after cerebral ischemia in normo-and diabetic hyperglycemic rats." (PMID 25389378, 2014). "Eight minutes of cerebral ischemia induced the increased immunoreactivity of ICAM-1 in the small blood vessels of the normoglycemic animals at 3 and 6 days of reperfusion." (PMID 25389378, 2014). "It has been shown that FTY720 could ameliorate brain ischemia‐induced edema using two mechanisms: first, by decreasing ICAM‐1 expression and neutrophil activation; second, by direct action on endothelial S1P receptors." (PMID 33969931, 2021). "It seemed that the enhanced KLF4 could suppress the vascular endothelial expression of three CAMs including E-selectin, VCAM-1, and ICAM-1 after cerebral ischemia." (PMID 32264912, 2020). "Upregulation of IL-17 mRNA can induce the expression of IL-1, IL-6, IL-8, TNF-α, and ICAM-1, which may aggravate the secondary inflammatory reaction after cerebral ischemia." (PMID 32194375, 2020). "Similarly, ICAM-1 immunoblockade reduces ischemic brain injury and neutrophil accumulation in both rat and rabbit models of cerebral ischemia." (PMID 28115020, 2017). "Furthermore, 4R was found to decrease the infarct size in mice and rats subjected to brain ischemia via inhibition of ICAM-1 expression and restoration of Akt phosphorylation." (PMID 28611572, 2017). "ICAM-1 levels were measured to determine if EP1 modulates ICAM-1 in cerebral ischemia." (PMID 26648273, 2015). "ICAM-1 plays an important role in initiating neuro-inflammation after cerebral ischemia." (PMID 25389378, 2014). "Thus, we concluded that metformin exerts its protective effect after cerebral ischemia partly through diminished ICAM-1 expression." (PMID 25315906, 2014). "Stachydrine hydrochloride (15, 30 and 60 mg/kg) was administered in a repetitive cerebral ischemia reperfusion mouse model, and it reduced the levels of TNF-α, ICAM-1, and MPO." (PMID 35795571, 2022). "Here, we examined the expression levels of VCAM-1, ICAM-1, E-selectin, and CD9 in vivo and in vitro to confirm the effects of CD151 on endothelial cell adhesion molecules within the TEMs in cerebral ischemia." (PMID 34022890, 2021). "Intercellular adhesion molecule-1 (ICAM-1), P-selectin, E-selectin and integrins have been demonstrated to be overexpressed in animal models of cerebral ischemia and interference with these adhesion molecules reduces leukocyte infiltration and tissue injury." (PMID 34572077, 2021). "Cerebral ischemia results in activation of NF-κB in microglia which release inflammatory factors, such as TNF-α, ICAM-1, IL-6." (PMID 32153408, 2020). "Expression of adhesion molecules (e.g., ICAM-1 and VCAM-1) is mediated by activation of the NF-κB pathway, which is typically studied as an indicator of inflammation in models of cerebral ischemia." (PMID 32019570, 2020). "NF-κB is involved in the inflammatory responses that potentiate cerebral ischemic damage, thus activating many genes involved in the pathogenesis of cerebral ischemia, such as iNOS, IL-1β, TNF-α, ICAM-1, COX-2, and IL-6." (PMID 29220411, 2017). "RT-PCR analysis indicated that TNF-α, IL-1, ICAM-1, and MMP-9 mRNA levels were elevated and suggested that NF-κB was activated by ROS produced during the 14-min global brain ischemia and 24-h reperfusion injury." (PMID 26230326, 2015).
Cerebral ischemia (continued). "IL-6 up-regulates the expression of adhesion molecules, such as intercellular adhesion molecule-1 (ICAM-1), selectins and integrins on endothelial cells, leukocytes and platelets, during cerebral ischemia, which leads to secondary neuronal damage." (PMID 23497639, 2013). "Intercellular adhesion molecule-1 (ICAM-1) was found to appear in the postischemic no-reflow regions during cerebral ischemia." (PMID 35795571, 2022). "The results showed that BZP improved focal cerebral ischemia-reperfusion injury in rats and PC12 cells treated with Na2S2O4 in dose/concentration-dependent manners through inhibition of production of 15-HETE and expression of NF-κB, IL-6, TNF-α, and ICAM-1." (PMID 32153408, 2020). "Delayed expression of intercellular adhesion molecule-1 in astrocytes may be regulated by TNF-α and its receptors after brain ischemia." (PMID 21152396, 2010). "In a study targeting endothelial integrin ligand ICAM-1, anti-ICAM-1 murine antibody was shown to be effective in experimental cerebral ischemia, but offered no neuroprotective benefits in the clinical phase III trial, rather was associated with adverse clinical outcomes." (PMID 34572077, 2021). "Studies done in rodent models of cerebral ischemia show that FTY720 ameliorates the influx of leukocytes in the ischemic brain and reduces the expression of pro-inflammatory cytokines (IL-1β and IFN-γ) and adhesion molecules, such as intercellular adhesion molecule-1 (ICAM-1)." (PMID 27617002, 2016). "In contrast to its effects on the expression of ICAM-1 and VCAM-1 molecules that promote firm adhesion—iNO had no apparent effect on E-selectin or P-selectin expression following cerebral ischemia." (PMID 38102677, 2023).
rheumatoid arthritis (44 papers, 1992 to 2026). A chronic, systemic autoimmune disorder characterized by inflammation in the synovial membranes and articular surfaces. "Polymorphisms of the ICAM1 gene also play a crucial role in the pathological process of rheumatoid arthritis." (PMID 36553455, 2022). "Other cytokines implicated in rheumatoid arthritis pathology, such as serum levels of soluble intercellular adhesion molecule-1 (sICAM-1) and vascular endothelial growth factor (VEGF), were significantly reduced in male rats at 6 hours post extract treatment." (PMID 31612077, 2019). "These ICAM-1 properties have been linked to rheumatoid arthritis." (PMID 38650775, 2024). "IF staining confirmed the expression of intercellular adhesion molecule‐1 (ICAM‐1) (an indicator related to the activation of synovial endothelial cells in rheumatoid arthritis) in HUVECs under 3D culture conditions." (PMID 40985312, 2025). "According to one study, the ICAM-1 levels in plasma and synovial fluid were significantly greater in rheumatoid arthritis patients compared to normal healthy controls." (PMID 38650775, 2024). "Blocking of ICAM-1 has been proven useful in rheumatoid arthritis, but targeting ICAM-1 in tumors have shown disappointing results." (PMID 36505809, 2022). "ICAM-1 and its receptors are critically involved in various inflammatory pathological diseases, such as experimental allergic encephalomyelitis, rheumatoid arthritis, and GVHD." (PMID 33692786, 2021). "For example, an anti-ICAM-1 monoclonal antibody (R6.5, enlimomab) was tested in clinical trials in patients with rheumatoid arthritis, acute stroke, and to treat acute rejection of renal transplants and burn injury." (PMID 31337787, 2019). "The ICAM1 rs1799969 polymorphism may be associated with the occurrence of Bechet’s disease (BD), rheumatoid arthritis (RA), and cancer." (PMID 30473535, 2018). "Genes showing lower levels of expression in AD included ICAM-1, IL-1B, CCR1, IFIH1, SOCS1, TNFAIP3 and TNFSF13B, which are strongly associated with acute and chronic inflammation and adult rheumatoid arthritis." (PMID 26310571, 2015). "The intercellular adhesion molecule-1 (ICAM-1) was found by immunostaining chondrocytes in cartilage from three patients with rheumatoid arthritis." (PMID 18475445, 1992). "Moreover, Dexamethasone-integrated MSC-based biomimetic liposomes enhance their affinity for polarized macrophages via the LFA-1/ICAM-1 interaction, thereby improving the therapeutic efficacy in rheumatoid arthritis (RA)." (PMID 40465163, 2025). "In addition, treatment of synovial fibroblasts derived from rheumatoid arthritis patients with TQ (1–5 μM) for 24 h decreased ICAM-1 gene expression despite pre-stimulation with TNF-α." (PMID 35723378, 2022). "Several studies in systemic autoimmune and chronic inflammatory diseases, e.g., systemic lupus erythematosus (SLE), rheumatoid arthritis, or chronic lung diseases describe increased sCD62L serum levels, together with other elevated adhesion molecules, such as ICAM-1 and VCAM-1." (PMID 32365632, 2020). "Many previous studies have shown increased levels of the soluble form of both ICAM-1 and E-selectin released into the systemic circulation that correlate with the activity and severity of several diseases such as rheumatoid arthritis, Grave’s disease and systemic vasculitis." (PMID 31284382, 2019). "IL-18 enhanced the expression of intercellular adhesion molecule-1 (ICAM-1) in human myelomonocytic cell lines, and ICAM-1 and vascular cell adhesion molecule-1 (VCAM-1) in endothelial cells and rheumatoid arthritis synovial fibroblasts." (PMID 33732720, 2021). "It is also consistent with one study that showed that LTαβ, which only binds LTβR, induced mRNA or protein expression of ICAM-1, and several chemokines including CCL5, in rheumatoid arthritis-derived fibroblast-like synoviocytes." (PMID 29616048, 2018).
rheumatoid arthritis (continued). "ICAM-1 can be induced by interleukin-1 (IL-1β) and TNF-α and is expressed by the A549 cells, human airway smooth muscle cells, or human rheumatoid arthritis synovial fibroblasts." (PMID 25675437, 2015). "Recently, we also showed that IL-1β induced ICAM-1 expression via p42/p44 MAPK and JNK1/2 in human rheumatoid arthritis synovial fibroblasts." (PMID 25675437, 2015). "KEGG pathway analysis of the upregulated proteins in ENTPD1+CD55+ cells indicated enrichment for proteins involved in rheumatoid arthritis (e.g., HLA-DRA, ICAM1) and ECM–receptor interaction (e.g., type I collagen, Laminin subunit alpha-5, integrin-subunit alpha-6)." (PMID 38612896, 2024). "In pathologies such as rheumatoid arthritis, IL-18 has been shown to promote migration, adhesion and activation of leucocytes through the release of different factors such as SDF1/CXCL12 and VCAM1/ICAM1." (PMID 24778454, 2014). "In addition, a study of rheumatoid arthritis have shown that HA modulates inflammation based on its molecular weight, and HMW-HA was reported to inhibit the production of pro-inflammatory mediators and down-regulate NF-kB by binding to ICAM-1." (PMID 36080383, 2022).
psoriasis (43 papers, 2005 to 2025). An autoimmune condition characterized by red, well-delineated plaques with silvery scales that are usually on the extensor surfaces and scalp. "In the current study, we found that it could regulate the production of TNF-α, IL-8, IL-23 and ICAM-1 associated with psoriasis." (PMID 28464025, 2017). "We identified that the Ile684Ser variant within the TYK2 gene, which may act through the ICAM1 gene, is associated with many traits including psoriasis, Crohn’s disease, and infections, and may suggest integrins and their receptors as potential drug targets." (PMID 29091937, 2017). "Network pharmacology analysis showed that 20 transdermal constituents were associated with potential therapeutic targets for psoriasis, including TNF, MMP9, TLR4, ICAM1, EGFR, and MAPK14." (PMID 41012530, 2025). "Consistently gene expression analysis in aorta samples showed elevated markers of endothelial activation, such as Icam1 and Vcam1 in psoriasis-like condition." (PMID 40599782, 2025). "Efalizumab inhibits binding between LFA-1 and intercellular adhesion molecule 1 (ICAM1) to affect several T cell pathways involved in psoriasis, including T cell activation, adhesion, and transendothelial trafficking." (PMID 37115692, 2023). "In psoriasis, it was demonstrated that the intercellular adhesion molecule-1 (ICAM-1) and phosphorylation of c-Jun N-terminal kinase (JNK), the extracellular signal-regulated kinase 1⁄2 (ERK 1⁄2) and p38 MAPK were elevated, along with the activation of TNF-α." (PMID 36875194, 2023). "It should be mentioned that ICAM-1 has been considered a biomarker of psoriasis, which is downregulated in patients treated with golimumab." (PMID 37298466, 2023). "Efalizumab, an mAb against integrin αLβ2 (LFA-1, ligand for ICAM-1), reached the market for psoriasis treatment." (PMID 35463298, 2022). "In the current study, the levels of IL-6, IP-10/CXCL10, MIP-3α/CCL20, and ICAM-1 were upregulated in M5-stimulated HaCaT cells (in vitro model of psoriasis)." (PMID 35209199, 2022). "ICAM-1 is an important adhesion molecule for T-cell recruitment in psoriatic skin lesions, and the overexpression of ICAM-1 was observed in epidermal keratinocytes from psoriasis patients." (PMID 35209199, 2022). "Transendothelial migration in inflammatory dermatoses such as psoriasis depends on the expression of E-selectin and ICAM-1 adhesion molecules on hematopoietic and endothelial cells." (PMID 34685372, 2021). "ICAM1 mRNA expression level in psoriasis involved skin was 4.0-fold lower (p < 0.001) and in non-involved skin it was 5.0-fold lower (p < 0.001) compared with healthy control skin." (PMID 34884858, 2021). "Evidence suggests that intercellular adhesion molecule-1 (ICAM-1) is a main mediator of psoriasis pathogenesis." (PMID 32659890, 2020). "On the other hand, inhibition of IL-36γ released by IL-17A-treated keratinocytes impaired either proliferation or ICAM-1 expression both in HDMECs and in an in vivo murine model of psoriasis." (PMID 32352958, 2020). "VEGF has been shown to induce the upregulation of ICAM-1 in a transgenic mouse model of psoriasis, whereby its effects on ICAM-1 expression were demonstrated to be the result of an enhanced VEGF/NRP-1 interaction in a retinal mouse model." (PMID 31817879, 2019). "In the skin network, we identify KDs such as ICAM1, IL15, STAT1, TNFAIP3, and GRB2 to be the network hubs connecting numerous genes in the psoriasis-associated supersets." (PMID 30642337, 2019). "When compared with healthy controls, supernatants from psoriasis macrophages have an increased ability to stimulate and adhere to the endothelium (ICAM-1)." (PMID 29535706, 2018). "Supernatant derived from IL-36γ-stimulated, psoriasis macrophages induced significantly more ICAM-1 expression when compared with healthy macrophages." (PMID 29535706, 2018).
psoriasis (continued). "The PheWAS results for the variant encoding p.Ile684Ser in TYK2 (which we noted was working through the ICAM1 gene) highlighted a known risk association with IBD and a protective association for psoriasis." (PMID 29091937, 2017). "Dexamethasone, which has been commonly used for atopic treatment of psoriasis and dermatitis and here was used as positive control, it also showed significantly lowering effects for the mRNA levels of IL-8, IL-23, and ICAM-1, except for TNF-α." (PMID 28464025, 2017). "Efalizumab is an antibody drug used in the treatment of psoriasis which inhibits the association between LFA-1 and ICAM-1." (PMID 26690684, 2015). "The expression of ICAM-1 is not only intensely and locally increased in endothelial and lymphocytic cells in psoriatic lesions but also directly related to the severity of psoriasis." (PMID 34354596, 2021). "Therefore, it will be interesting to investigate the factors that contribute to the lycopene-mediated inhibition of ICAM-1 expression in psoriasis." (PMID 32659890, 2020). "CTSH was surrounded by CTSS, CTSD and other critical factors involved in complement and adhesion (e.g., C3 and ICAM1) in the psoriasis network, suggesting that it might trigger inflammatory responses by regulating the neighbors in the network." (PMID 30642337, 2019). "In addition, the upregulation of ICAM-1 expression in keratinocytes has been observed in several inflammatory dermatoses, such as psoriasis, atopic dermatitis, and lupus erythematosus." (PMID 29443928, 2018). "ICAM-1 can be strongly produced and plays a key role in pathogenesis of psoriasis." (PMID 28464025, 2017). "Indeed, Raptiva, the recently-approved antibody therapeutic for psoriasis, directly targets the ICAM-1/LFA-1-mediated T cell adhesion process." (PMID 15960850, 2005). "ICAM-1 provides adhesion sites between neutrophils and lymphocytes and activates vascular endothelial cells to release inflammatory mediators, and it may contribute to psoriasis." (PMID 33323018, 2021). "In addition, several studies have shown that some natural products, such as glycyrrhizin and gambogic acid, could improve psoriasis by inhibiting the expression of ICAM-1." (PMID 34354596, 2021). "In addition, ICAM-1 was an important molecule to recruit immunocytes to the skin and contribute to psoriasis, which could be triggered by TNF-α in diverse cell types." (PMID 32515468, 2020). "The infiltration of leukocytes into the skin could be regarded as one of characteristics of inflammatory immune responses in the psoriasis, and the increment of intercellular adhesion molecule 1 (ICAM-1) expression in the psoriatic lesions could improve the infiltration of leukocytes." (PMID 31181689, 2019). "While there are no marketed drugs targeting ICAM1, efalizumab is an integrin alpha-L/beta-2 inhibitor which was approved for the treatment of psoriasis but then withdrawn due to a potential risk to patients of developing progressive multifocal leukoencephalopathy (FDA." (PMID 29091937, 2017). "The LFA-1/ICAM-1 interaction may allow formation of these aggregates, and in turn these T cell/dendritic cell aggregates may be responsible for the perpetuation and chronicity of psoriasis lesions." (PMID 17324275, 2007). "In psoriasis, MMP9 also significantly upregulates the mRNA levels of ICAM-1, IL1β and CXCL1 in vascular endothelial cells (VECs), which enables VECs interaction with more leukocytes." (PMID 34122426, 2021). "p65 and STAT3 cooperatively recruit intercellular adhesion molecule (ICAM)-135, which play an important role in inflammatory cell migration in psoriasis; moreover, PPL reduced LPS-induced ICAM-1 expression." (PMID 31924750, 2020). "Adhesion molecules include intercellular adhesion molecule-1 (ICAM-1) and vascular cell adhesion molecule-1 (VCAM-1), which play an important role in the infiltration of T cells into psoriasis lesion sites." (PMID 32659890, 2020).